PHGDH (phosphoglycerate dehydrogenase)
Diseases named in the same sentence as PHGDH in open-access papers (continued):
Sharing a sentence is not in itself a finding about the gene and the disease.
cancer (continued). "Given that CBR-5884 is a selective inhibitor of phosphoglycerate dehydrogenase that is involved in de novo serine synthesis in cancer cells, and to make sure that the growth perturbation is not due to serine starvation, 5 mM serine was also added to the media ± ethanolamine." (PMID 38587428, 2024). "Because these specific metabolic pathways are direct targets of cancer therapies, inhibitors targeting PHGDH in tumors with expression of components of these pathways may lead to the development of resistance." (PMID 38945960, 2024). "Therefore, not only the use of one drug but also the combination of a previously used drug with a PHGDH inhibitor and diet therapy are effective in treating cancer through PHGDH." (PMID 38945960, 2024). "Together, low-PHGDH expression determines exogenous Ser dependency in cancer." (PMID 39706853, 2024). "Interestingly, a recent study demonstrated that although high PHGDH activity supports cancer cell proliferation, cells with low PHGDH expression exhibit higher metastatic potential in breast cancer." (PMID 36823188, 2023). "Researchers found that PHGDH was upregulated in several cancers." (PMID 37127605, 2023). "It has been reported that several lncRNAs functioned in cancer progression by targeting PHGDH." (PMID 37127605, 2023). "Therefore, PHGDH is a promising cancer therapeutic target, and several PHGDH inhibitors have been identified as anti-cancer molecules." (PMID 37664062, 2023). "Here, to capitalize on the link between PKM2 and serine biosynthesis pathway in NSCLC, we used the PKM2 inhibitor (PKM2-IN-1) and PHGDH inhibitor (NCT-503) to evaluate the anti-cancer effect and the mechanism of PKM2-IN-1 in combination with NCT-503 in A549 cells and a xenograft model." (PMID 37284309, 2023). "Lnc01564 binds to PHGDH in a competitive manner, weakening the suppression of PHGDH induced by miR-107/103a-3p, leading to an increase in PHGDH expression and promoting hepatocellular carcinogenesis and cancer cell survival." (PMID 37394582, 2023). "PHGDH is a metabolic enzyme involved in the serine synthetic pathway and it appears to play a central role in supporting cancer growth and proliferation, so it is a promising drug target for cancer therapy." (PMID 36831448, 2023). "Current studies have shown that PHGDH is upregulated in expression in many tumors, and PHGDH inhibitors have been reported to inhibit PHGDH-dependent cancer cell growth and survival, suggesting that it could be a target for cancer therapy." (PMID 36803157, 2023). "Moreover, there is evidence linking triglyceride levels to PHGDH DNA methylation, suggesting a potential regulatory role of this enzyme in triglyceride metabolism in cancer." (PMID 37775701, 2023). "PHGDH inhibitors such as NCT-502 could enhance ferroptosis to suppress the malignant progression of cancer via an interaction between PHGDH and PCBP2." (PMID 37886960, 2023). "In addition, by interacting with actin family member 15, PHGDH prevents its own degradation and promotes the phenotype and malignant transformation of cancer stem cells (CSCs) through ROS imbalance in HCC." (PMID 37187454, 2023). "Moreover, the use of PHGDH inhibitors can increase the sensitivity of cancer cells to chemotherapy drugs." (PMID 37187454, 2023). "The results showed that PHGDH was significantly over-expressed in cancer tissues of BCa patients." (PMID 36147463, 2022). "Serine biosynthesis pathway mediated by PHGDH has been recognized as one of the patterns of cancer-specific metabolism, and its inhibition has been reported to have specific therapeutic effects on several cancer cells with high PHGDH expression." (PMID 36319669, 2022). "In this respect, inhibition of 3-phosphoglycerate dehydrogenase (PHGDH), the rate limiting enzyme for de novo serine biosynthesis, turned out to be a promising therapeutic strategy to overcome resistance in metabolically-driven cancers." (PMID 36340043, 2022).
cancer (continued). "The development of such metabolic inhibitors could treat cancer patients with the amplification or overexpression of PHGDH." (PMID 36144843, 2022). "Notably, while PHGDH does seem to be important for the development of some cancers, including metastatic breast cancer, observations in other cancer models have suggested that this enzyme is dispensable for tumor development." (PMID 35316216, 2022). "This and other work motivated the development of PHGDH inhibitors as potential cancer treatments." (PMID 35045283, 2022). "PHGDH gene expression significantly promotes cancer-cell proliferation." (PMID 35344765, 2022). "Importantly, silencing PHGDH gene can significantly affect the growth of PHGDH-dependent cancer, making the enzyme a new target for cancer treatment." (PMID 36105480, 2022). "PHGDH is the first key enzyme of SSP that plays a cancer-promoting role in multiple tumors." (PMID 36699468, 2022). "Western blot also verified the high PHGDH expression in cancer tissues." (PMID 36147463, 2022). "PHGDH has been demonstrated to be highly expressed in a wide variety of cancers." (PMID 33503424, 2021). "Human 3-phosphoglycerate dehydrogenase (PHGDH) is an important enzyme in the process of serine synthesis, and the serine and glycine has offered sufficient energy and metabolites accelerating the proliferation of cancer cells." (PMID 33763366, 2021). "Moreover, the elevation of PHGDH expression is usually related to cancer progression and poor prognosis." (PMID 33763366, 2021). "Accumulating evidence suggests that PHGDH is a promising therapeutic target for cancer." (PMID 34957102, 2021). "Many of these transcriptional regulators are altered in cancer and contribute to increased serine synthesis flux, but PHGDH expression was also found to be amplified through copy number gain of a genomic region on chromosome 1p12 in a subset of breast and melanoma." (PMID 33669382, 2021). "As a consequence, the combination of dietary serine restriction and pharmacological inhibition of phosphoglycerate dehydrogenase (PHGDH), a rate-limiting enzyme in the serine biosynthetic pathway, has shown antitumoral effects on mouse cancer models resistant to each treatment alone." (PMID 34256164, 2021). "PHGDH is highly expressed in many cancer cells and plays a critical role to support a variety biosynthetic processes important for cell proliferation), thereby our findings might provide a novel potential therapeutic targets for cancer therapy." (PMID 34178629, 2021). "Therefore, they decided to undertake a PHGDH knockdown (KD) and demonstrated that it decreased the stemness characteristics and promoted Embryonic Carcinoma Stem-Like Cells differentiation in multilineage." (PMID 34072080, 2021). "Elevated PHGDH expression drives a reliance on certain metabolic pathways that cancer therapeutics directly target, thus resulting in a series of inhibitors to which cancers with increased PHGDH can develop resistance." (PMID 33511334, 2020). "PHGDH is overexpressed and/or genomically amplified in more than 16% of cancer lines." (PMID 31979167, 2020). "Interestingly, several PPP enzymes and 3-phosphoglycerate dehydrogenase (PHGDH) were found upregulated in some cancer." (PMID 32211323, 2020). "Therefore, increased levels of PHGDH, while contributing to tumorigenicity, can contribute to the innate or acquired resistance of cancers to current chemotherapies." (PMID 33511334, 2020). "An understanding of the downstream mechanistic actions of PHGDH activity can unveil new therapies that could have action in PHGDH-overexpressed cancers." (PMID 33511334, 2020). "There have been reports that PHGDH inhibition or depletion leads to apoptosis in various cancers." (PMID 32386122, 2020). "In addition, PHGDH inhibitors significantly inhibited cancer cell growth, and synergistic effects with GC treatment were observed both in vitro and in vivo in BC." (PMID 32386122, 2020).
cancer (continued). "A high PHGDH expression is observed in aggressive subtypes of cancers." (PMID 32824193, 2020). "Additionally, A-RAF, a RAF paralog, increases activation of PKM2 in the presence of serine, offering an additional target for sorafenib and another resistance mechanism in PHGDH-overexpressed cancers." (PMID 33511334, 2020). "Thus, inhibition of PHGDH in cancers overexpressing this key enzyme affects glutamine flux into the TCA cycle as well as serine synthesis leading to growth arrest." (PMID 32477466, 2020). "Interestingly, The overexpression of PHGDH is often associated with progression of cancers, and the inhibitors of PHGDH reduce the glycolysis and suppress the growth of cancers." (PMID 32664979, 2020). "However, recently DSF was also reported as one of the first phosphoglycerate dehydrogenase (PHGDH) inhibitors, a tetrameric enzyme catalyzing the initial step of the serine synthetic pathway that is highly expressed in numerous cancer types." (PMID 30894617, 2019). "PHGDH was shown overexpressed in some tumors, and its downregulation impaired cancer growth." (PMID 31744229, 2019). "In some cancer cells, a large proportion of glucose is used in the serine de novo synthesis pathway, wherein 3-phosphoglycerate is used by D-3-phosphoglycerate dehydrogenase (PHGDH)." (PMID 30631755, 2018). "Furthermore, this study also demonstrated that depletion of PHGDH has a more pronounced effect on growth inhibition in cancer cells with amplified PHGDH expression." (PMID 30250195, 2018). "This approach might be much less effective in cancer cells with low PHGDH, suggesting PHGDH expression as a predictive marker of response to therapies based on inhibitors of serine synthesis." (PMID 28649560, 2017). "Exploring this strategy may be timely, since other approaches to PHGDH inhibition have already been shown to reduce cancer progression in mice." (PMID 29262655, 2017). "PHGDH is amplified in a number of cancers, including 6% of breast cancers and 40% of melanomas." (PMID 28177894, 2017). "We have investigated substrate analogues to assess whether PHGDH might possess other enzymatic roles that could explain its occasional over-expression in cancer, as well as to help with the design of specific inhibitors." (PMID 29262655, 2017). "In such cancer cell lines PHGDH depletion resulted in decreased proliferation effects, which could not be rescued by increased serine supplementation to the media." (PMID 29262655, 2017). "This promiscuity of PHGDH could be particularly relevant in explaining the role of PHGDH in cancer and may suggest PHGDH as a tractable target for inhibitor design." (PMID 29262655, 2017). "PHGDH has been identified as a gene frequently amplified in different cancers." (PMID 26918450, 2016). "However, dependence on increased PHGDH expression extends beyond production of serine alone, and further studies of PHGDH function are necessary to elucidate its role in cancer cells." (PMID 25926973, 2015). "Moreover, cancer cells with PHGDH amplification were found to exhibit increased metabolic flux into serine biosynthesis, which is known to play a dual role in redox balance and providing nucleotide units to support cancer cell proliferation." (PMID 26356530, 2015). "Increased activity of serine biosynthesis pathway enzymes has been hypothesized to support increased nucleotide biosynthesis in cancer, although cell lines vary in their dependence on PHGDH expression for growth as xenograft tumors." (PMID 25926973, 2015). "If true, the requirement of additional serine for growth would hold weight, highlighting the need for future studies to determine how this happens and what it means in terms of the broader network of metabolic mechanisms in cancer and the potential for PHGDH as a metabolic oncogene." (PMID 25574168, 2014).
cancer (continued). "In this paper, I review the historic progression of our understanding of the role of PHGDH in cancer from the early work by Snell through its reemergence and rise to prominence, culminating in an assessment of subsequent work and what it means for the future of PHGDH." (PMID 25574168, 2014). "Where the discussion becomes interesting is in the correspondingly consistent finding across multiple types of cancer that PHGDH overexpression may directly promote oncogenesis." (PMID 25574168, 2014). "In some cancer cells, a relatively large amount of glycolytic carbon is diverted into serine and glycine metabolism through phosphoglycerate dehydro-genase (PHGDH), which could explain the increased glycine concentration in the samples containing tumor cells." (PMID 23613877, 2013). "Ultimately, PHGDH embodies three cardinal paradoxes of cancer metabolism: a metabolic lifeline under stress that becomes a therapeutic liability; a promoter of primary tumorigenesis that may suppress metastasis; and an enzymatic workhorse moonlighting as an epigenetic regulator." (PMID 41486146, 2026). "This aspect led us to hypothesize that the diversity among CRC patients in basal PHGDH protein levels and its dynamic regulation along the treatment with 5-FU could result in differential therapy efficacy, finally influencing cancer progression and patients’ outcome." (PMID 40640948, 2025). "Interestingly, although increased PHGDH expression supports cancer cell proliferation, studies have demonstrated that low PHGDH induces abnormal protein glycosylation through activation of the hexosamine-sialic acid pathway, thus non-catalytically enhancing cancer spread and metastasis." (PMID 40078876, 2025). "Moreover, given the metabolic plasticity of cancer cells, PHGDH inhibition may trigger compensatory serine uptake via transporters." (PMID 40660426, 2025). "Interestingly, 2-HG can be derived also from the promiscuous activity of some key metabolic enzymes, including malate dehydrogenase (MDH), lactate dehydrogenase (LDH), and phosphoglycerate dehydrogenase (PHGDH), and can accumulate in cancer cells in both its enantiomeric forms (i.e., D- and L-2HG)." (PMID 38216942, 2024). "Moreover, the inhibition of PHGDH in cancer cells suppresses cell proliferation and tumorigenesis." (PMID 38945960, 2024). "Therefore, PHGDH is now recognized as a significant factor in cancer research." (PMID 38945960, 2024). "In bronchial epithelial cells, adaptations occurred in a similar fashion as in cancer cells, but serine synthesis and serine to glycine conversion, as assessed by label enrichments and gene expression levels, were generally lower than in (PHGDH positive) cancer cells." (PMID 38515202, 2024). "Furthermore, it was deduced that methyl caffeate could be developed into a supplement used for chemoprevention as it elicits apoptosis by selectively inhibiting 3-phosphoglycerate dehydrogenase (PHGDH) enzyme which is highly expressed in cancer cells." (PMID 39478959, 2024). "In addition, studies demonstrated PHGDH may be involved in cancer and tumour resistance to chemotherapy." (PMID 38577610, 2024). "Therefore, additional research should be conducted to determine whether existing PHGDH inhibitors can be applied to other types of cancer in addition to those for which their efficacy is already known." (PMID 38945960, 2024). "Targeted inhibition of PHGDH may affect cancer growth only in serine-poor environments." (PMID 37664062, 2023). "The AAV-mediated ectopic expression of PHGDH-T57A and PHGDH-R135W in the liver of wild-type mice that retains normal serine synthesis did not change the levels of 3-PGA or other glycolytic intermediates, emphasizing a causative role of availability of 3-PGA itself in cancer growth." (PMID 37726403, 2023).
cancer (continued). "Several studies in recent years have shown that PHGDH inhibitors selectively block the growth of PHGDH-dependent cancer cells and that silencing the PHGDH gene significantly affects the development of PHGDH-dependent cancers, making the enzyme a new target for cancer therapy." (PMID 36803157, 2023). "Therefore, know-down of PHGDH serves to be a therapeutic target for treating cancer." (PMID 36147463, 2022). "3- Phosphoglycerate dehydrogenase (PHGDH) is the rate-limiting enzyme that catalyzes the conversion of 3-Phosphoglyceric acid (3-PG) into 3-Phosphohydroxy pyruvate (3-PPyr) in the first step of serine synthesis pathway and perform a critical role in cancer progression." (PMID 36144843, 2022). "Inhibition of PHGDH may be a promising strategy for cancer therapy." (PMID 35365231, 2022). "Thus, this study has unveiled the potential of phenolic compounds, which could serve as novel candidates for the development of PHGDH inhibitors as anti-cancer agents." (PMID 36144843, 2022). "Additionally, O. japonica inhibited tumor-specific metabolism in proliferating cancer cells by suppressing the expression of α-enolase, phosphoglycerate dehydrogenase (a regulator of the serine synthesis pathway), and fatty acid synthase, resulting in lower biosynthesis demands from cancers." (PMID 33567572, 2021). "However, both PHGDH and PSAT1 are regulators and associated with an increased risk for multiple cancer progression and metastasis, indicating a possible link between dieting and cancers." (PMID 33921318, 2021). "Cancer cell lines that overexpress the rate-limiting enzyme involved in the serine biosynthesis pathway PHGDH are sensitive to the pharmacologic inhibition of PHGDH, suggesting that targeting this enzyme may have a therapeutic role." (PMID 33652666, 2021). "Moreover, α-ketothioamides could selectively strain the proliferation of cancer cells with elevated PHGDH expression." (PMID 32226297, 2020). "Furthermore, this is the first report indicating that PHGDH expression might be accelerated by hypomethylation in cancers." (PMID 32386122, 2020). "Importantly, the PHGDH gene is often amplified in certain cancers." (PMID 32386122, 2020). "Moreover, we speculate that targeting PHGDH could suppress serine biosynthesis, leading to the inhibition of cancer cell viability through downregulation of vital cell constituents." (PMID 32386122, 2020). "Thus, we speculate that the acceleration of serine biosynthesis through increased PHGDH expression in BC might upregulate production of cell constituents (proteins, nucleic acids and lipids) that are necessary for cancer cell growth." (PMID 32386122, 2020). "However, whether increased PHGDH expression in tissues promotes cancer initiation or progression and what impact increased enzyme activity has on normal physiology has not been studied." (PMID 31331318, 2019). "As PHGDH is the rate-limiting enzyme of serine synthesis, this finding implies substantial cell-to-cell variability in the level of de novo serine biosynthesis from the glycolytic intermediate, 3-phosphoglycerate (3PG) in each cancer cell line when grown in complete growth medium." (PMID 29925909, 2018). "If small molecules are identified using either approach, they could provide insight into whether the ability to inhibit 3-PG to PHP conversion alone is the relevant PHGDH function in cells and help understand the role of this enzyme in cell proliferation and human cancer." (PMID 25926973, 2015). "Therefore, both an understanding of whether an epitope tag will impact PHGDH function and methods to produce recombinant enzyme that reflects endogenous protein activity in cells are necessary to determine the role of PHGDH in human cancer and normal tissues." (PMID 25926973, 2015).